MIR26B (microRNA 26b)
Synonyms: hsa-mir-26b; MIRN26B; miR-26b
Gene: MicroRNA gene on chromosome 2 (218,402,646 to 218,402,722, forward strand). Ensembl gene ENSG00000199121.
Gene Ontology:
Biological process: miRNA-mediated post-transcriptional gene silencing
Cellular component: RISC complex
Homologues: Orthologues: chimpanzee ptr-mir-26b (100% identical), macaque MIR26B (95% identical), guinea pig MIR26B (94% identical), pig MIR26B (92% identical), rabbit MIR26B (92% identical), mouse Mir26b (91% identical), rat Mir26b (91% identical), tropical clawed frog xtr-mir-26-2 (65% identical). Paralogues in human: MIR26A1 (71% identical), MIR26A2 (65% identical).
Diseases named in the same sentence as MIR26B in open-access papers:
MIR26B is named in the same sentence as 4 diseases in open-access papers, as found by Europe PMC text mining. Sharing a sentence is not in itself a finding about the gene and the disease. The quoted sentences say what the papers report.
liver cirrhosis (1 paper, 2025). "Remarkably, both Mir26b-3p and –5 p were significantly elevated in the plasma of liver cirrhosis patients, suggesting – at least – a strong association between Mir26b and the development of MASH in humans." (PMID 40261813, 2025). "To further evaluate the importance of Mir26b in liver diseases in humans, we have measured the expression levels of Mir26b-3p and Mir26b-5p in the plasma of healthy subjects and patients with liver cirrhosis." (PMID 40261813, 2025). "Besides the in vivo studies, we also examined the expression levels of Mir26b in the plasma of liver cirrhosis patients." (PMID 40261813, 2025).
liver fibrosis (1 paper, 2025). "Overall, these results imply a protective role of Mir26b in liver fibrosis, which is linked to an altered expression of Tgfb." (PMID 40261813, 2025). "Moreover, Tgfb expression was increased by the Mir26b deficiency, leading to more hepatic fibrosis." (PMID 40261813, 2025). "Collagen deposition in liver sections was determined by a Sirius-red staining, which showed that a knockout of Mir26b significantly exacerbated hepatic fibrosis." (PMID 40261813, 2025). "Hepatic fibrosis is mainly caused by the activation of the fibrogenic factor TGF-β, which is also confirmed in the current study as Mir26b knockout mice displayed a higher amount of Sirius red positive area and an increased expression of Tgfb." (PMID 40261813, 2025). "Therefore, this study focused on the role of Mir26b in MASH showing that mice deficient in Mir26b presented with a higher hepatic lipid content, higher levels of pro-inflammatory cytokines, and an increased number of infiltrated macrophages in the liver and exacerbated hepatic fibrosis." (PMID 40261813, 2025). "As such, we also investigated the influence of Mir26b on hepatic fibrosis in mice." (PMID 40261813, 2025). "Another gene involved in liver fibrosis, that is ‘actin alpha 2’ (Acta2), trended towards an elevated expression in mice lacking Mir26b." (PMID 40261813, 2025).
steatosis (1 paper, 2025). Increased lipid within the cytoplasm of cells. "Moreover, pathological scoring of the Oil-red-O staining unveiled that the Apoe-/-Mir26b-/- mice showed a clear tendency towards increased steatosis compared to controls, especially of macrovesicular steatosis." (PMID 40261813, 2025).
MIR26B also shares sentences with these, for which no sentence is quoted: liver diseases (1 paper).